GAP43 (growth associated protein 43)
Diseases named in the same sentence as GAP43 in open-access papers (continued):
Sharing a sentence is not in itself a finding about the gene and the disease.
neuropathy (9 papers, 2010 to 2022). A disorder affecting the nervous system that manifests with pain, tingling, numbness, and/or muscle weakness. "HuD is upregulated and contributes to pain hypersensitivity to mechanical and cold stimulation in antiretroviral-evoked painful neuropathy by regulating spinal ryanodine receptor-2 or GAP43 or contributes to thermal hot hyperalgesia in oxaliplatin-induced neuropathy by regulating GAP43." (PMID 31013625, 2019). "We have recently used GAP-43 staining in skin biopsies in patients with sarcoidosis related neuropathy and showed that GAP-43+ nerves increased in a dose dependent manner after a relatively short period of pharmacological intervention to stimulate nerve regeneration." (PMID 30837937, 2019). "This study was aimed at understanding the cellular and molecular mechanisms involved in oxaliplatin-induced neuropathy, and showed that adult rat DRG neurons treated with oxaliplatin in vitro, undergo dose-dependent loss of neurite length, density, Gap43 expression, and neuronal number." (PMID 21106058, 2010). "As such, we cannot exclude that GAP-43 may be a valid marker at earlier stages of neuropathy." (PMID 36383568, 2022). "This study aimed to investigate the temporal expressions of activating transcription factor-3 (ATF-3), growth-associated protein-43 (GAP-43), neuropeptide Y (NPY) and galanin in traumatic and non-traumatic rat models of neuropathies associated with NP." (PMID 25070481, 2015).
memory impairment (7 papers, 2021 to 2025). "Downregulation of GAP43 expression has been associated to various psychiatric conditions in humans and evokes hippocampus-dependent memory impairments in mice." (PMID 39168654, 2024). "Both Cistanche deserticola polysaccharide and total glycosides upregulate the expression of synapsin, growth-associated protein 43 (GAP43), PSD-95, and BDNF, enhancing synaptic plasticity in the hippocampal region and improving learning and memory impairments." (PMID 40584613, 2025). "This exposure led to memory impairment and the downregulation of neuronal proteins like GAP-43 and CaMKII." (PMID 39596398, 2024). "This could be partially explained by CSF GAP-43 being a biomarker of synaptic dysfunction, and the accumulation of tau pathology being correlated with synaptic dysfunction and memory impairment." (PMID 36253408, 2022). "The changed hippocampal synaptic protein GAP-43, SYP, PSD-95 levels, serum corticosterone levels, and neuroinflammation were found in sleeping deprivation related memory impairment mice." (PMID 35126189, 2021).
myocardial infarction (7 papers, 2013 to 2022). Gross necrosis of the myocardium, as a result of interruption of the blood supply to the area, as in coronary thrombosis. "NGF and GAP43 are nerve growth factors, which can cause excessive regeneration and uneven density of cardiac nerves after myocardial infarction while Sema-3A is a nerve growth inhibitor, which can inhibit the excessive growth of sympathetic nerves." (PMID 34471416, 2021). "Meanwhile, growth-associated protein-43 (GAP-43), a marker of nerve sprouting, and tyrosine hydroxylase (TH), a marker of the sympathetic nerve, were significantly elevated in myocardial infarction mice." (PMID 35178131, 2022). "Electroacupuncture (EA) therapy enhances cardiac function by inhibiting mRNA and protein expression of GAP43 in a study of myocardial infarction in coronary artery disease." (PMID 36222281, 2022). "The protein content of NGF and GAP43 in the marginal area of the MI group increased significantly while the protein level of Sema-3A decreased 28 days after myocardial infarction." (PMID 34471416, 2021). "NGF rapidly released and the concentration of NGF and GAP43 in the area around the infarction increased immediately after myocardial infarction." (PMID 34471416, 2021). "Studies have found that sympathetic nerve remodeling after MI has been observed in patients with myocardial infarction and animal models, and the densities of TH and GAP43 positive nerve fibers have increased." (PMID 34471416, 2021). "In this study, YQHX can significantly regulate nerve remodeling related factors and reduce the protein content of TH, NGF, and GAP43 in the marginal area of infarction and the stellate ganglion in rats with myocardial infarction." (PMID 34471416, 2021). "During the recovery from myocardial infarction, cardiac nerve sprouting and sympathetic hyperinnervation significantly enhanced in the infarcted area, manifested with the increased numbers of both GAP-43 and TH positive nerves in the CB, IBZ and LVFW of the MI animals." (PMID 28732009, 2017). "A number of experiments have verified that the expression of GAP43 factor and NGF increase at the same time, indicating the rapid growth of related nerves, especially after myocardial infarction." (PMID 34471416, 2021).
Anxiety (6 papers, 2021 to 2024). Intense feelings of nervousness, tension, or panic often arise in response to interpersonal stresses. "GAP43 haploinsufficiency in mice also causes connectivity-associated alterations such as an aberrant functional somatotopy, multiple sensorimotor deficits, anxiety, and decreased sociability." (PMID 39168654, 2024). "In the present study, we examined the effects of PS, ELF‐EMF, and simultaneously PS and ELF‐EMF on anxiety‐like behaviors, and expression of synaptic plasticity associated proteins (BDNF and GAP‐43) and neural cell apoptotic factor, cas‐3." (PMID 36942730, 2023). "Accordingly, serotonin, MDA, dopamine, immobility time (FST), anxiety index (EPM), number of trials (MWM), latency in outer edge (OFT), Zn content, GAP-43 immunoexpression, and neurofilament disposition variables are grouped together and highly correlated with PC1." (PMID 37442924, 2023).
Parkinson disease (6 papers, 2020 to 2025). A progressive degenerative disorder of the central nervous system characterized by loss of dopamine producing neurons in the substantia nigra and the presence of Lewy bodies in the substantia nigra and locus coeruleus. "GAP43, which plays an important role in axon elongation, synaptogenesis, and neuronal sprouting, is downregulated in the brains of patients with Parkinson’s Disease." (PMID 41050398, 2025). "In the following sections, GAP-43 and BASP1 will be discussed in the context of Alzheimer’s and Parkinson’s Disease, two neurodegenerative diseases in which they have been studied the most." (PMID 33015061, 2020).
peripheral nerve injury (6 papers, 2012 to 2024). Injury to a peripheral nerve. "It has been shown that increasing the expression of GAP-43 can enhance axonal regeneration and functional recovery in various nerve injury models, including peripheral nerve injury." (PMID 37664821, 2023). "GAP-43 immunostaining is a widely used marker for regenerating axons in experimental models of peripheral nerve injury." (PMID 30778286, 2019). "While the stimulatory effect of a single high dose of Dx on GAP-43 levels in the hippocampus of aged rats or of a Dx-releasing pellet on GAP-43 mRNA levels after peripheral nerve injury is known, this is the first study showing this effect in prenatally Dx-exposed rats." (PMID 39056739, 2024). "Since peripheral nerve injury induces JNK and c-Jun activation in DRG neurons, and since it has been proposed that c-Jun regulates the expression of growth-associated genes, we asked whether blockade of the JNK pathway affects injury-induced GAP43 activation." (PMID 22616849, 2012).
amyloid (5 papers, 2024 to 2025). "Similarly, GAP-43, which is linked to amyloid and tau pathologies, may help to monitor disease progression." (PMID 40864734, 2025). "This is in contrast to other synaptic proteins measured in CSF, for example, GAP‐43, SNAP‐25, and neurogranin, which are changed only in response to amyloid pathology." (PMID 40522075, 2025).
glioblastoma (5 papers, 2019 to 2025). The most malignant astrocytic tumor (WHO grade IV). "A tumor promoting function has been ascribed to highly-expressed GAP43 in human glioblastomas, where it is involved in the generation of so-called tumor microtubes." (PMID 31058089, 2019). "Specific targeting of GAP43, which is implicated in astrocytic brain tumorigenesis by promoting microtube formation and tumor cell invasion, could favor astrocytoma cell disconnection, thereby reducing the obstructive treatment resistance of these glioblastomas." (PMID 31058089, 2019). "Glioblastoma cells grown under stem conditions (GBMSCs) with a genetic knockdown of GAP-43." (PMID 34900673, 2021). "Furthermore, in glioblastoma cells, a short hairpin RNA‐mediated knockdown of GAP43, which is particularly relevant for the formation of neurite‐like membrane protrusions in neural and non‐neural cells, has shown a reduction of Cx43 GJ protein expression and intercellular TM connections." (PMID 39680504, 2025).
Tinnitus (5 papers, 2011 to 2021). Tinnitus is an auditory perception that can be described as the experience of sound, in the ear or in the head, in the absence of external acoustic stimulation. "A similar finding in the cochlear nucleus of rats demonstrated that GAP-43 (a synaptic plasticity associated protein) was upregulated in rats with SHL but not in rats with tinnitus." (PMID 27826232, 2016). "Other studies demonstrated increased cholinergic signalling in the VCN of hamsters, and elevated expression of GAP43 – a marker for plasticity – in the rat VCN following acoustic over-exposure, and that this could be linked to behavioural evidence of tinnitus." (PMID 24702651, 2014). "Indeed, we observed evidence for blast-induced elevations in GAP43 levels in the DCN (and NAC/HPN-07-specific mitigation) at nine weeks post-exposure, which has intriguing implications for tinnitus-related maladaptive plasticity in the DCN." (PMID 33411811, 2021). "GAP-43 up-regulation in VCN was significantly greater in noise-no-tinnitus (NT) rats than in noise-tinnitus (T) rats." (PMID 25266340, 2015).
type 2 diabetes (5 papers, 2015 to 2025). "In line with this, in patients with type 2 diabetes, immunofluorescence staining of GAP-43, a marker of neuronal regeneration, showed that they had more pain with increased branching of GAP-positive fibers." (PMID 37795274, 2023). "GAP43 is a neuronal protein that promotes neuronal growth and plasticity in the CNS and has been shown to be downregulated in iWAT of ob/ob mice, a mouse model for type II diabetes." (PMID 36028121, 2022). "Thus, the reduction of IENF density in both type 2 diabetes and fibromyalgia is accompanied by a reduction of GAP-43." (PMID 26503622, 2015).
brain infarct (4 papers, 2017 to 2021). "Similarly, exercise has been shown to promote axonal recovery as assessed by the upregulation of Tau and GAP-43 and is associated with functional improvement after cerebral infarction." (PMID 32670026, 2020). "Among these treatments, Que/mAb GAP43-Exo showed the best neuroprotective effects, as the cerebral infarction volume was the smallest." (PMID 34001136, 2021). "Meanwhile, GAP43 knockout enlarged brain infarct area and deteriorated the cognitive and motor dysfunctions of HI rats." (PMID 34663387, 2021). "The brain infarct volume is smaller, and neurological recovery is more markedly improved following Que/mAb GAP43-Exo treatment than following free Que or Que-carrying exosome (Que-Exo) treatment in a rat induced by MCAO/R." (PMID 34001136, 2021).
breast carcinoma (4 papers, 2018 to 2025). "Previously, nerve growth factor induced Gap43 positive nerve fiber sprouting and re-organisation has been reported in a mouse breast cancer bone metastasis model." (PMID 29988965, 2018).
colorectal cancer (4 papers, 2019 to 2023). A primary or metastatic malignant neoplasm that affects the colon or rectum. "We found the expression pattern of GAP43 in colorectal cancer cells was closely associated with cancer-linked DNA hypermethylation, and the methylation status of GAP43 promoter did not change in different colorectal cancer cell lines." (PMID 33402155, 2021). "Although GAP43 is expressed predominantly in the brain, it can also be found in some cases of colorectal cancer and inflammatory bowel disease." (PMID 37842184, 2023). "Analysis of the genomic data of colorectal cancer obtained from the TCGA database revealed a substantial silencing of GAP43 gene expression in colorectal cancer, with methylation modification being observed in its promoter region." (PMID 35884600, 2022). "In this study, we examined the GAP43 status with qRT-PCR and bisulfite genomic sequencing in colorectal cancer (CRC)." (PMID 33402155, 2021).
infarction (4 papers, 2017 to 2021). A localised pathological necrosis of tissue resulting from obstruction of the blood supply usually by a thrombus, an embolus, or vascular torsion. "Administration of RA reduced infarction volume, promoted neurological functional recovery and upregulated expression of GAP-43." (PMID 28380213, 2017).
injury (4 papers, 2012 to 2025). Damage inflicted on the body as the direct or indirect result of an external force, with or without disruption of structural continuity. "Nerve regeneration following nerve trauma has been associated with increased GAP-43 immunoreactivity in the DRGs." (PMID 25070481, 2015). "Several groups have reported an early up-regulation of GAP-43 protein or mRNA following nerve injury." (PMID 22325251, 2012). "A study found that XFZYD could reverse the reduction of BDNF and TrkB in the hippocampus caused by traumatic brain injury and increase the number of synaptic connections, as well as the expression of synaptic-related protein PSD95, axon-related protein GAP43, and neuron-specific protein TUBB3." (PMID 40430532, 2025). "Following nerve trauma, a number of neurochemical changes that have been linked to neuropathic pain mechanisms occur within DRG neurons, including the neuronal injury marker activating transcription factor-3 (ATF-3), neuropeptide Y (NPY), galanin and growth-associated protein-43 (GAP-43)." (PMID 25070481, 2015).
Brain atrophy (3 papers, 2018 to 2024). Partial or complete wasting (loss) of brain tissue that was once present. "In the present study, we demonstrated that GAP43, neurogranin, SNAP25, and synaptotagmin 1 were significantly changed in both EVs and CSF in patients with AD, and these changes corresponded to the severity of brain atrophy." (PMID 38528511, 2024). "The results showed that GAP43, SNAP25, neurogranin, and synaptotagmin 1 were decreased in neuronal-derived EVs but increased in CSF in patients with AD, and the changes corresponded to the severity of brain atrophy." (PMID 38528511, 2024).
cortical dysplasia (3 papers, 2017 to 2023). "Our findings demonstrate a relationship between epileptogenesis and upregulation of GAP-43 following a second hit in a model of cortical dysplasia." (PMID 29255203, 2017). "Conversely, the knockdown of GAP-43 in CD brains decreased interictal spike frequency, further suggesting a direct role of GAP-43 in cortical dysplasia and its upregulation in epileptogenesis." (PMID 29255203, 2017). "Besides being a protein involved in axon elongation and remodeling, it has recently been shown that GAP‐43 stimulates the increase of excitatory, but not inhibitory postsynaptic density scaffold proteins, contributing to epileptogenesis of a cortical dysplasia animal model." (PMID 35808864, 2022).
cyst (3 papers, 2011 to 2023). A sac-like closed membranous structure that may be empty or contain fluid or amorphous material. "Within the cyst, the majority of β-TubIII positive fibers also expressed GAP-43, whereas some of them were associated with MBP, indicating that myelination occurred at 8 weeks post-treatment." (PMID 21611127, 2011). "While astrocytic expression of AQP1 may be associated with cerebrospinal fluid secretion during cyst formation, its co-localization with growth-associated protein-43 (GAP-43) in neurons suggests a role in neuroplasticity and repair after injury." (PMID 37762642, 2023). "In order to quantify axon regeneration/sprouting across the cyst we investigated the presence of GAP-43 positive fibers and we expressed the relative value of GAP-43 immunopositive area as percentage of the total cyst area." (PMID 21611127, 2011). "Of interest the overexpression of GAP-43 mRNA at 7 dpi resulted in an increased immunopositivity to GAP-43 at 8 weeks: in treated animals the percentage of GAP-43 positive fibers within the cyst augmented more than twofold in comparison to controls." (PMID 21611127, 2011). "Small numbers of DcX and GAP43 positive fibres penetrated into tissue located within the cyst region, although these tended to be located immediately at the periphery of the cyst walls, and the number of fibres did not appear to differ between groups (data not shown)." (PMID 25105800, 2014). "Interestingly, we found a significantly greater synthesis of GAP-43 in 4G-BMHP1 group (12.94±2.03% of the whole cyst area) in comparison with saline (6.33±1.7% of the whole cyst area) and SCI control (5.84±1.29% of the whole cyst area) groups (Figure 2Bii)." (PMID 21611127, 2011). "Cyst size and morphological parameters, including the amount of degenerative tissue immediately surrounding the cyst, were assessed in toluidine blue stained sections and using immunohistochemical assessments of GFAP, β-III tubulin, DcX and GAP43 immunoreactivity at 28 days following SCI." (PMID 25105800, 2014).
diabetic neuropathy (3 papers, 2015 to 2022). A chronic, pathological complication associated with diabetes mellitus, where nerve damages are incurred due to diabetic microvascular injury involving small blood vessels that supply these nerves, resulting in peripheral and/or autonomic nerve dysfunction. "In contrast, other studies have demonstrated a decreased proportion of GAP-43+ IENFD in patients with diabetic neuropathy." (PMID 36383568, 2022). "GAP-43 staining has been applied to show altered cutaneous nerve fiber regeneration in patients with painful diabetic neuropathy." (PMID 30837937, 2019). "Interestingly, investigators in one study reported that patients with diabetic neuropathy and pain had higher GAP-43/PGP 9.5 ratios than patients with diabetic neuropathy without pain." (PMID 26503622, 2015).
frontotemporal dementia (3 papers, 2021 to 2022). Frontotemporal dementia (FTD) comprises a group of neurodegenerative disorders, characterized by progressive changes in behavior, executive dysfunction and language impairment, as a result of degeneration of the medial prefrontal and frontoinsular cortices. "Alterations in cerebrospinal fluid levels of GAP43 may aid in the clinical diagnosis of frontotemporal dementia." (PMID 33952343, 2021).
glaucoma (3 papers, 2008 to 2021). Increased pressure in the eyeball due to obstruction of the outflow of aqueous humor. "On the other hand, expression of miR-204 in glaucoma and optic nerve injury is high, which by disrupting GAP-43 disrupts the MyD88/TLR4/NFKB pathway and ultimately kills retinal cells (N.)." (PMID 34646884, 2021). "In in vivo experiments of both glaucoma and ONC treated with SC, GAP-43 positive parallel nerve fiber growth was detected within retrobulbar, unmyelinated parts of optic nerves; this outgrowth was absent in PBS-treated eyes." (PMID 27034151, 2016). "Staining with an antibody that recognizes predominantly phosphorylated NEFH revealed presumptive growth cone-like structures in the post laminar optic nerves of monkeys with experimental glaucoma, which also were positive for GAP43, whereas these structures were absent in control monkeys." (PMID 18822132, 2008). "The appearance of GAP43+ and phospho-NEFH+ growth cone-like structures in the optic nerve has not been previously reported in the nonhuman primate model or in human glaucoma." (PMID 18822132, 2008).